ATF6 (activating transcription factor 6)
Diseases named in the same sentence as ATF6 in open-access papers (continued):
Sharing a sentence is not in itself a finding about the gene and the disease.
tumor (continued). "As we will discuss in this review, the UPS routes are used by many proteins with key roles in promoting tumor chemoresistance, such as HSP70 family-like glucose-regulated protein 78 (GRP78) and ATF6." (PMID 35784465, 2022). "All three branches (through ATF4, XBP1s and ATF6) can directly bind to the promoter of VEGFA and other proangiogenic genes to alleviate tumor hypoxia." (PMID 36139473, 2022). "The qRT-PCR analysis also revealed a higher expression of PERK, ATF6, and GRP78 mRNAs in the tumor tissues than in the paracarcinoma tissues." (PMID 35090495, 2022). "For example, ATF6 regulates the expression of several pro-oncogenic proteins such as GRP78 and Notch1 and plays important roles in tumor growth and resistance to radiotherapy in GBM." (PMID 35150127, 2022). "In EOC, GRP78, ATF6α and PERK were highly expressed in EOC tissues compared to the normal tissues, and correlated with advanced tumor stages." (PMID 34149923, 2021). "We further confirmed that the regulation of the ATF6-mediated stimulation of the EGF pathway significantly enhanced the chemosensitivity of these tumors and delayed tumor relapse." (PMID 32630838, 2020). "In BxPC-3-derived xenograft tumor model, treatment with Tan IIA induced ER stress by up-regulating the levels of PERK, ATF6, caspase-12, IRE1α, eIF2α, p-JNK, CHOP, and caspase-3 and inhibited the tumor growth in vivo." (PMID 32265690, 2020). "The B-cell specific TF POU2F2 was predicted to inhibit tumor cell apoptosis and enhance transcription, and IRF4 in combination with ATF6 was predicted to play an important role in the development of hematopoietic neoplasm." (PMID 32585984, 2020). "Previous studies also suggested a functional link between ER stress response and tumor dormancy, which was supported by the findings that PERK activation inhibited cyclin D1 synthesis for G1 arrest, and that ATF6 was constitutively active in dormant cells." (PMID 33396303, 2020). "The present study demonstrates that the ATF6-mediated production of EGF in SCCs induces the recruitment of vascular endothelial cells and triggers tumor angiogenesis via the activation of the EGFR signaling in vascular endothelial cells." (PMID 32630838, 2020). "Immunohistochemistry results showed that tumour tissues displayed significantly elevated GRP78, PERK, ATF6 and IRE1α, relative to paracancerous tissues." (PMID 32672418, 2020). "In support of this notion, pharmacological or genomic approaches targeting ATF6 induced a significant decrease in EGF transcription and angiogenesis-stimulating activities in SCCs, effectively suppressing the SCC-derived tumor growth." (PMID 32630838, 2020). "For example, ER proteins such as XBP1, PERK, ATF6 and ATF4 that are involved in ER stress have been reported to participate in tumor growth and metastasis." (PMID 33014334, 2020). "Like flavonoid molecules, another ATF6 inhibitor melatonin modulates important kinases FAK, SRC and ROCK1 involved in tumor migration." (PMID 31064137, 2019). "The authors showed that the stimulation of ADAM17 expression by severe hypoxia in several tumour cell lines occurs as a consequence of the activation of the PERK/eIF2α/ATF4 pathway and activating transcription factor 6 (ATF6)." (PMID 30709842, 2019). "ATF6 protein expression was positively correlated with CIP2A protein expression (P < 0.001) and tumor stages (P = 0.007)." (PMID 30063110, 2018). "TUN at a dose of 10μg was able to increase the expression of UPR genes (Grp78, PERK, XBP1, and ATF6) and IAP protein Survivin, which indicates the role of ERS in tumor promotion." (PMID 30326660, 2018). "In other tumour types, ATF6α overexpression has been proposed to be a target against cancer stem cells (CSC), due to the nuclear translocation of ATF6α under the effect of tunicamycin in CSC population." (PMID 30134550, 2018).
tumor (continued). "As an UPR-stimulating gene, ATF6 plays an important role in tumor genesis, and ASNS gene is important in tumor genesis due to its function of synthesis of asparagine, which is an essential amino acid for normal tissue or tumor growth." (PMID 28629319, 2017). "Further tests of ATF6 and ASNS mRNA levels in HCC tumor tissues and corresponding non tumor tissues should be done." (PMID 28629319, 2017). "In fact, the data showed ER homeostasis disruption in tumor cells, since expressions of some genes of UPR and GRP78/GADD153 protein levels were elevated by Amblyomin-X treatment, as well as ATF-6α transport." (PMID 27015684, 2016). "For tumours LS3x, LS21, LS43 and MS8x, the genes ATF6 and DUSP12 showed the highest amplification level in general, 3–5 fold in LS3x and 5–10 fold in LS21 and LS43 (except ATF6), and particularly high copy numbers (>10 fold) in MS8x." (PMID 16274472, 2005). "LMS15 and LS43 showed the same expression levels of both ATF6 and DUSP12 as the tumours with normal copy number of the genes." (PMID 16274472, 2005). "Second, given the complexity of ER stress signalling, it will be important to determine whether RNF39 selectively modulates specific branches of the UPR (e.g. PERK–eIF2α–CHOP vs. ATF6 or IRE1) and how this regulation impacts tumour cell fate decisions." (PMID 41457280, 2026). "Using UPR inhibitors and in loss-of-function experiments for transcription factors such as, XBP1, ATF4 and ATF6, we find that C5aR1 expression is complementarily regulated by multiple UPR pathways; highlighting the strong dependence of tumour cells on UPR-dependent C5aR1 signalling." (PMID 40695778, 2025). "Endoplasmic reticulum stress (ERS) dynamically regulates cell fate decisions within the tumor microenvironment (TME) through the PERK, IRE1α, and ATF6 pathways of the unfolded protein response (UPR), forming an “ERS-Death Axis” interconnected with apoptosis, autophagy, pyroptosis, and ferroptosis." (PMID 41407677, 2025). "Although the role of ATF6 in cancer immune escape mechanisms has not been fully elucidated, several studies have shown that it regulates tumor occurrence and progression." (PMID 40547943, 2025). "In addition, we also analyzed the survival of genes which constituted PLP2+ Tumor EPCs score, and the results showed that only four of them (SPIB, ATF6, PLAGL1, ERG) were statistically significant (P<0.05)." (PMID 38482016, 2024). "Additionally, ATF6 amplifies apoptosis in sunitinib-resistant KIRC cells through the endoplasmic reticulum stress pathway, thereby influencing tumor progression." (PMID 38292868, 2024). "Tumor cells within the stem subtypes had higher ER13 expression than did those within the differentiated compartments, and ATF6 displayed a similar expression pattern to ER13." (PMID 39324706, 2024). "ATF6 is the most mysterious of the three pathways, and the relationship between ATF6 and tumor MDR has not been widely explored." (PMID 37790807, 2023). "In the presence of TG, the anti-tumor effect of each ATF6 inhibitor, with or without ER stress-inducing drugs, was slightly enhanced." (PMID 37704840, 2023). "To determine whether PPM1H inhibits tumor growth in vivo, we established stable PPM1H- or ATF6-overexpressing and PPM1H knockdown Hep 3B2.1-7 cells." (PMID 37456776, 2023). "This may suggest that ATF6 and PERK act in concert to suppress numerous types of cell death to ensure tumor progression and metastasis." (PMID 37067519, 2023). "Rg3 can promote the apoptosis of tumor cells through IRE1α, PERK and ATF6 pathways." (PMID 37790807, 2023). "Furthermore, during tumor angiogenesis, VEGF also induces cancer cell progression via the activation of PERK and ATF6 pathways." (PMID 35205628, 2022). "The expression of Atf6 was not detectable in a sufficient number of samples within the tumor-free or tumor-bearing groups, therefore no conclusions were drawn for this branch of the UPR (Data not shown)." (PMID 33718372, 2021).
tumor (continued). "Interestingly, UPR kinetic studies in HCC revealed that IRE1α is activated during tumor initiation and the PERK pathway during tumor progression, while ATF6 is only moderately activated in developed tumors." (PMID 34671553, 2021). "To date, ERS associated UPR has attracted much attention from researchers and oncologists, as it could influence tumor proliferation and aggravation, and determine cell fate via three pathway branches initiated by IRE1α, PERK, and ATF6." (PMID 35004850, 2021). "Furthermore, activating transcription factor 6 (ATF6) induced the upregulation of EGF, and its antagonism effectively suppressed these SCC-mediated events and inhibited tumor recurrence after chemotherapy." (PMID 32630838, 2020). "In intestinal cancer cells, early growth response protein 1 (EGR1), an important transcription factor that controls the expression of chemokines/cytokines involved in tumor metastasis such as CCL2 and CXCL1, is positively regulated upon activation of PERK and ATF6." (PMID 31064137, 2019). "The ERSR is regulated by ATF6, IRE1, and PERK in normal cells, while it is often deregulated and promotes tumorigenicity, as the depletion of tumor suppressors or activation of oncogenes, favors cells that survive during high protein synthesis and metabolic stress in cancer cells." (PMID 30857233, 2019). "ATF6 and XBP1 are two most important factors mediating the UPR and their downregulation could induce tumour cell death in aggressive cancers like PDAC, thereby acting as a regulatory mechanism in the overall process of tumourigenesis." (PMID 31795960, 2019). "Cell treated by specific inhibitors of the UPR downstream mediators or mice malignant cells lacking IRE1α, XBP-1, PERK, or ATF6 are more sensitive to hypoxia, with higher production of ROS, lower angiogenesis, delayed tumour progression and metastasis." (PMID 29415493, 2018). "Therefore, both ATF6 signaling and GRP78 appear to contribute to tumor adaptation to microenvironmental challenges by promoting protein folding." (PMID 25941664, 2015). "However, our studies show that the UPR pathway was enhanced in the normal tissues and tumor lesions in these mice, as manifest by increased levels of GRP78/BiP, a known target of ATF6." (PMID 22363765, 2012). "In addition, two genes known to be transcriptionally activated by ATF6, glucose-regulated protein 78 kDa and -94 kDa (GRP78 and GRP94), were shown to be over-expressed in the tumours that showed over-expression of ATF6." (PMID 16274472, 2005). "For tumours LS3x, LS21, LS43 and MS8x, the genes ATF6 and DUSP12 showed the highest amplification level in general, suggesting that one of them may be the target for this amplification." (PMID 16274472, 2005). "The expression levels of ATF6 and DUSP12 were determined by quantitative real-time RT-PCR, and in general the expression level of ATF6 and DUSP12 reflected the amplification level in the different tumours." (PMID 16274472, 2005). "The elevated activity of ATF6 and aryl hydrocarbon receptor nuclear translocator (ARNT) in γδ T cells may synergistically assist these cells in adapting to the hypoxic and metabolic stresses present in the tumor microenvironment." (PMID 41155287, 2025). "Among the UPR branches, ATF6α has been shown to promote prostate cancer progression by upregulating PLA2G4A (cytosolic phospholipase A2)-mediated arachidonic acid metabolism, leading to elevated prostaglandin production and resistance to ferroptotic cell death in tumor cells." (PMID 41228282, 2025). "To assess the impact of ATF6 knockdown on tumor progression, we treated mice harboring pre-established palpable tumors with sucrose-supplemented water lacking or containing Dox and tracked tumor volumes over 3 weeks." (PMID 39324706, 2024).
tumor (continued). "Tumour cells activate the unfolded protein response (UPR) to cope with ERS, which is controlled by three ER transmembrane sensors: inositol-requiring transmembrane kinase/endoribonuclease 1α (IRE1α), activating transcription factor 6 (ATF6), and protein kinase R–like ER kinase (PERK)." (PMID 37221596, 2023). "Additionally, rhein inhibited cell proliferation, the production of adenosine triphosphate, and mitochondrial transmembrane potential in tumor cells but promoted apoptosis, the levels of glucose regulatory protein 78(GRP78) and activating transcription factor 6 (ATF6)." (PMID 34516329, 2021). "On the other hand, ATF6α prolongs survival of dormant tumor cells, but not proliferative squamous carcinoma cells, through transactivation of the Ras homolog enriched in brain (Rheb; a critical activator of the mammalian target of rapamycin [mTOR]) and thus activation of mTOR signaling." (PMID 28860159, 2017). "The role of ATF6 in tumor chemoresistance has not been extensively studied at present." (PMID 26622781, 2015). "The primary role of the UPR is to provide survival signaling pathways required for tumor growth by dissociating GRP78, which regulates the protein folding process, from three endoplasmic reticulum stress sensors (including PERK, IRE1α and ATF6) that are consequently phosphorylated and activated." (PMID 24396487, 2014). "Lack of anti-apoptotic GRP78 induction could contribute to cell death in maintaining the three transducers of ER stress (PERK, IRE1α and ATF6) under an activated status and down-regulation of GRP78 is known to sensitize tumor cells to apoptosis induced by current anti-cancer therapies." (PMID 21179554, 2010). "Unfortunately, the roles of ATF6 and PERK pathways in tumor‐infiltrating NK cells have not been clearly demonstrated." (PMID 40035165, 2025). "Sustained expression of the three mutants did not impede tumor cell viability and neither PERK/eIF2α nor ATF6 branches of the UPR were activated in these conditions." (PMID 26325176, 2015). "Accordingly in that study, neither the PERK nor ATF6 branches were involved but interestingly, IRE1α inhibition was required for engaging immunogenic cell death in the BRAF-mutant setting, showing how IRE1α mediates tumor resistance through immune evasion." (PMID 35347108, 2022). "Notably, in chondrosarcoma, only a single study reports that PRP-1 (proline-rich polypeptide), a toll-like receptor ligand, increases the expression of PERK, eIF2α, ATF4, CHOP, ATF6, IRE1α, and XBP1; however, no studies have yet investigated the functional role of the UPR in this tumor." (PMID 41228282, 2025).
cancer (152 papers, 2008 to 2026). A tumor composed of atypical neoplastic, often pleomorphic cells that invade other tissues. "When activated, the ATF6 transcription factor is more frequently translocated to the nucleus in various types of cancer, such as HCC and Hodgkin’s lymphoma, and has been associated with metastasis and recurrence." (PMID 40278350, 2025). "Strikingly, the combination of small eccDNAs originated from phospholipase D1 (PLD1) and activating transcription factor 6 (ATF6) had great multi‐cancer diagnostic value." (PMID 37649244, 2023). "Various studies have shown that ATF6 is implicated in cancer cell survival." (PMID 34073612, 2021). "Evolving evidence in the literature points to the role of ATF6 activation in the reprogramming of lipid metabolism in cancer." (PMID 41301006, 2025). "Targeted inhibition of GRP78, IRE1α, PERK, and ATF6 can effectively enhance the efficacy of existing cancer treatments and significantly promote cancer cell apoptosis." (PMID 40547943, 2025). "We also provide an overview of pharmacological agents targeting specific UPR pathways, such as GRP78 inhibitors, IRE1α inhibitors, PERK inhibitors, and ATF6 inhibitors, with the aim of developing more effective cancer therapies." (PMID 40547943, 2025). "ATF6 is a key component in the precise regulation of the ER protein response, but its role in cancer has been studied less than the other two transducers." (PMID 40278350, 2025). "Some studies suggest inhibitory effects of melatonin on ATF6 cleavage while others indicate elevated ATF6 cleavage in different cancer cells." (PMID 40873119, 2025). "Endoplasmic reticulum unfolded protein responses contribute to cancer development, with activating transcription factor 6 (ATF6) involved in microbiota-dependent tumorigenesis." (PMID 40890536, 2025). "Persistent ER stress in tumors activates UPR sensors (IRE1α, PERK, ATF6), driving cancer proliferation, metastasis, immune evasion, and drug resistance." (PMID 40547943, 2025). "This connection between lysosomes and the ER becomes especially important, as UPR transducers (PERK, IRE1, and ATF6) coordinate with the lysosomal autophagic pathway in cancer cells to maintain homeostasis." (PMID 40723802, 2025). "Liver metabolic dysfunction, fibrosis, and cancer progression have been shown to correlate with the activation of UPR pathways including ATF6." (PMID 40801087, 2025). "The activation of the PERK, IRE1, and, to a lesser extent, ATF6 signaling pathways has been observed in various cancers following oncogene activation." (PMID 40278350, 2025). "Given its ability to modulate both cell survival and metastatic behaviors, ATF6 represents an attractive therapeutic target for limiting cancer progression." (PMID 40223122, 2025). "In regards to cancer, ATF6 was shown to promote proliferation and migration through MAPK signaling in cervical cancer." (PMID 39026685, 2024). "There are several studies that ATF6 is related to the occurrence and progression of various cancers." (PMID 38896161, 2024). "The role of intrinsic ATF6 represents an avenue for further research in cancer cells, which remains largely uninvestigated." (PMID 39188936, 2024). "A previous study showed that ATF6 mediates chemotherapy resistance in cancer cells by promoting their survival." (PMID 39080273, 2024). "Cdc20 catalyzes the polyubiquitination of TPD52 to mark it for degradation, leading to the downregulation of ATF6 and ER stress as well as the progression of cancers." (PMID 39401430, 2024). "Correlation analysis using transcriptomic data from the TCGA database revealed that RPN1 expression positively correlates with the ER stress-related genes PERK (EIF2AK3) and ATF6 in multiple cancer types." (PMID 39749324, 2024).